DLK2 (delta like non-canonical Notch ligand 2)
Description:
Regulates adipogenesis.
Synonyms: DLK-2; EGFL9; MGC2487
Tractability: Antibody: UniProt predicts a signal peptide or a membrane-spanning region.
Gene: Protein-coding gene on chromosome 6 (43,450,351 to 43,456,632, reverse strand). Ensembl gene ENSG00000171462.
Subcellular location: Membrane
Subcellular location (Human Protein Atlas): Nucleoplasm; Nucleoli; Vesicles
Gene Ontology:
Molecular function: Notch binding; calcium ion binding; identical protein binding
Biological process: negative regulation of Notch signaling pathway; regulation of fat cell differentiation
Cellular component: membrane
Genetic constraint (gnomAD): Loss-of-function variants: 9 observed, 29.88 expected, observed/expected ratio (o/e) 0.3, 90% interval 0.18 to 0.53. The upper end of that interval is the gene's LOEUF score, 0.53, which puts it in group 2 of 6, group 1 being the genes least tolerant of losing a copy. Missense variants: 387 observed, 527.32 expected, observed/expected ratio (o/e) 0.73, 90% interval 0.67 to 0.8. Synonymous variants: 169 observed, 199.34 expected, observed/expected ratio (o/e) 0.85, 90% interval 0.75 to 0.96.
Homologues: Orthologues: chimpanzee DLK2 (99% identical), macaque DLK2 (99% identical), pig DLK2 (93% identical), guinea pig DLK2 (92% identical), mouse Dlk2 (92% identical), dog DLK2 (92% identical), rat Dlk2 (87% identical), rabbit DLK2 (81% identical), zebrafish dlk2 (46% identical), Caenorhabditis elegans egas-3 (21% identical), Caenorhabditis elegans apx-1 (21% identical), Caenorhabditis elegans egas-2 (21% identical), and 5 more. Paralogues in human: DLL3 (32% identical), CD93 (24% identical), FBLN7 (20% identical), CD248 (18% identical), CRELD1 (17% identical), CRELD2 (16% identical), WIF1 (16% identical), CLEC14A (14% identical).
Diseases named in the same sentence as DLK2 in open-access papers:
DLK2 is named in the same sentence as 16 diseases in open-access papers, as found by Europe PMC text mining. Sharing a sentence is not in itself a finding about the gene and the disease. The quoted sentences say what the papers report.
breast carcinoma (5 papers, 2019 to 2024). "In this work, we explored the effects of different DLK2 expression levels on the characteristics of MDA-MB-231 breast cancer cells." (PMID 35163478, 2022). "Recently, DLK2 was described as overexpressed in lethal prostate cancers, uveal melanoma, breast cancer cell lines and in patient tissues spanning three breast cancer subtypes (Luminal A, Luminal B, and Triple Negative)." (PMID 35163478, 2022). "Our data revealed for the first time that different levels of DLK2 expression in MDA-MB-231 breast cancer cells can produce opposite effects on tumor invasiveness and growth rate both in vitro and in vivo." (PMID 35163478, 2022). "In this work, we studied whether different levels of DLK2 expression influenced the breast cancer characteristics of MDA-MB-231 cells." (PMID 35163478, 2022). "Our data support an important role of DLK2 as a protein that can finely regulate NOTCH signaling and affect the tumor properties and growth dynamics of MDA-MB-231 breast cancer cells." (PMID 35163478, 2022). "Alternatively, DLK2 might promote osteogenesis via a NOTCH-independent pathway, such as through the activation of the cMET receptor, as suggested in studies related to breast cancer metastasis." (PMID 39473022, 2024). "Most likely, the level of NOTCH activation, modulated by DLK1 and DLK2, may led to opposite effects on the invasive properties of MDA-MB-231 breast cancer cells and tumor cell growth in vitro and in vivo." (PMID 35163478, 2022). "To further study this possibility, we decided to analyze the expression levels of the JAG1, which encodes for Jagged1, one of the most important canonical NOTCH receptor ligands in breast cancer, as well as the expression levels of the four NOTCH receptor genes in our DLK2-overexpressing cells." (PMID 35163478, 2022). "We also analyzed the effects of different levels of DLK2 expression on other signaling pathways already known to be affected by DLK1 expression and NOTCH signaling, which ultimately affect gene expression and cell behavior in breast cancer cells." (PMID 35163478, 2022). "Furthermore, our data show that the level of activation of NOTCH and the degree of phosphorylation of the kinases studied in this work, which appear to be modulated by the expression levels of DLK2, may lead to opposite effects on the features of MDA-MB-231 breast cancer cells." (PMID 35163478, 2022). "DLK2, a non-canonical inhibitor of NOTCH signaling, was previously shown to be involved in skin and breast cancer." (PMID 35163478, 2022). "Nevertheless, it was recently reported that the overexpression of DLK2 (EGFL9) protein does not affect the proliferation of mammary epithelial cell, and that the downregulation of its expression does not affect the proliferation of mouse 4T1 and human SUM159 metastatic breast cancer cell lines." (PMID 35163478, 2022).
melanoma (3 papers, 2022 to 2025). A malignant, usually aggressive tumor composed of atypical, neoplastic melanocytes. "Notch family genes were also upregulated by human interface cells (DLL1, DLL3 and DLK2) and confined human melanoma cells (NOTCH2NLA, DLK2 and DLL4)." (PMID 40866703, 2025). "It was reported that, similarly to DLK1, DLK2 affects the growth of SK-MEL-2 melanoma cells, and the nature of its effects depends upon DLK2 expression levels and the degree of inhibition of NOTCH1 activation." (PMID 35163478, 2022). "In the DLK2 biology, DLK2 can promote the oncogenic processes of melanoma cells through the inhibition of NOTCH signaling." (PMID 35456435, 2022). "In previous works, we showed that DLK2 functions as an inhibitor of NOTCH signaling in mouse preadipose cells and in human melanoma cells." (PMID 35163478, 2022).
Anxiety (1 paper, 2022). Intense feelings of nervousness, tension, or panic often arise in response to interpersonal stresses. "Another study reported that mice with a deficiency in Delta-like 2 (a member of the NOTCH ligand family) gene (Dlk2) exhibited downregulated Fkbp5 expression and increased vulnerability to anxiety-like behavior." (PMID 35705957, 2022).
colon cancer (1 paper, 2022). "Another gene, PLEKHB2 (also called evectin-2), negatively correlated with the DLK2 level, plays a critical role in the YAP oncogenic pathway of proliferating cells, and it is also downregulated in colon cancer." (PMID 35456435, 2022).
hepatoma (1 paper, 2011). "We show here the characterization of the mouse Dlk2 transcript in several preadipocitic and hepatoma cell lines, as well as in adult brain, spleen, heart, liver, and testis." (PMID 22185379, 2011). "We first analyzed the expression level of Dlk2 in several cell lines, and decided to use the mouse hepatoma cell line AT3F as a source of RNA, due to its high level of Dlk2 expression." (PMID 22185379, 2011).
metastatic melanoma (1 paper, 2024). A melanoma that has spread from its primary site to another anatomic site. "DLK2 belongs to the Notch/Delta/Serrata family, and it has been reported to regulate metastatic melanoma cell proliferation in a dose-dependent manner." (PMID 38474039, 2024).
osteoporosis (1 paper, 2023). A condition of reduced bone mass, with decreased cortical thickness and a decrease in the number and size of the trabeculae of cancellous bone (but normal chemical composition), resulting in increased fracture incidence. "Therefore, we sought to determine whether Dlk2 deficiency could prevent OVX-induced osteoporosis." (PMID 37669921, 2023).
triple-negative breast carcinoma (1 paper, 2022). An invasive breast carcinoma which is negative for expression of estrogen receptor (ER), progesterone receptor (PR), and human epidermal growth factor receptor 2 (HER2). "The effects on the growth and invasion capabilities of MDA-MB-231 cells observed upon the reconstitution of DLK1 or upon DLK2 overexpression, are consistent with the role of NOTCH signaling in the growth of triple-negative breast cancer cells." (PMID 35163478, 2022). "We estimate that this property is suitable for studying the potential effects of the forced overexpression of DLK2 on triple-negative breast cancer cell growth without interfering with the expression of its homolog, DLK1." (PMID 35163478, 2022).
cancer (4 papers, 2017 to 2022). A tumor composed of atypical neoplastic, often pleomorphic cells that invade other tissues. "In addition, DLK2 expression levels also affected some members of other cell signaling pathways implicated in cancer, such as ERK1/2 MAPK, AKT, and rpS6 kinases." (PMID 35163478, 2022). "For the prognositc analyses, the UALCAN database was used to study the tumoral DLK2 expression profiles in variable ccRCC patients with different disease stages, tumor grades, metastatic status, cancer subtypes, ages, patient races, and genders." (PMID 35456435, 2022). "That, all models using DLK2 and KIT had positive coefficients for their expression values (indicating increased expression of the markers is associated with increased BC risk) is consistent with their generally accepted roles in cancer development and progression." (PMID 28798985, 2017). "Firstly, the DLK2 expression in Pan-cancer was analyzed using the TIMER tool, and TNMplot was used to analyze the DLK2 level in ccRCC tissues and normal renal tissues." (PMID 35456435, 2022). "From the Pan-cancer analysis using the TIMER tool, DLK2 was significantly upregulated in the tumor tissues compared with the non-tumor tissues in many cancer types, including ccRCC (*** p < 0.001)." (PMID 35456435, 2022). "This suggests that, in addition to their effect on SNAI2 and CDH gene expression, both DLK1 and DLK2 may affect other shared mechanisms that modulate the invasive properties of MDA-MB-231 and other cancer cells." (PMID 35163478, 2022). "Furthermore, the cancer subtype, metastatic status, patient race, and gender did not significantly affect the expression of DLK2 in ccRCC tissues." (PMID 35456435, 2022).
tumor (4 papers, 2019 to 2024). "The upregulation of DLK2 in tumor tissues was associated with advanced stage, high tumor grade, and poor survival outcome in ccRCC patients." (PMID 35456435, 2022). "In the RCC study, the DLK1 vaccine in murine models results in the inhibition of RCC growth, but also in the compensatory expression of DLK2 by tumor-associated pericytes." (PMID 35456435, 2022). "Using the TNMplot analysis, DLK2 was upregulated in paired ccRCC tissues compared with paired non-tumor tissues (*** p < 0.001), and the expression of DLK2 in the ccRCC tumor was significantly higher than in the kidney from the non-ccRCC donor (*** p < 0.001)." (PMID 35456435, 2022). "In the miRNA analysis, the expressions of miR-296, miR-331, and miR-28 targets (possible oncogenes) were positively correlated with the DLK2 level, and previous studies indicate that miR-296, miR-331, and miR-28 sever as tumor suppressors." (PMID 35456435, 2022). "To study the effects of different DLK2 expression levels on tumor growth in vivo, we subcutaneously injected MDA-MB-231 cells transfected with empty-vector cells, or HDLK2SL or HDLK2SH cell pools into nude mice and measured their growth rate for six weeks." (PMID 35163478, 2022). "It has been reported that delta-like 1 homologue (DLK1) participates in the tumor microenvironmental remodeling of ccRCC, but the relationship between delta-like 2 homologue (DLK2, a DLK1 homologue) and ccRCC is still unclear." (PMID 35456435, 2022). "Expression levels of DLK2 and IL15RA were also aligned across survival risk groups with IL15RA being relevant given its evolving role in targeted therapies to overcome resistance and improve anti-tumor effect." (PMID 39123468, 2024). "According to the Pearson’s correlation analysis, the tumor DLK2 level was negatively correlated with the expressions of M1 macrophage markers such as HLA class II histocompatibility antigen, DR α chain (HLA-DRA) (* p = 0.0278), CD11c (integrin α X, ITGAX) (p = 0.0557), and CD86 (p = 0.0783)." (PMID 35456435, 2022). "Furthermore, the DLK2 level was negatively correlated with the expressions of miR-496 and miR-373 targets (possible tumor suppressor genes)." (PMID 35456435, 2022). "Moreover, depending on the level of inhibition of NOTCH1 activation generated by different levels of DLK2 expression, cell proliferation, cell cycle dynamics, cell apoptosis, cell migration, and tumor growth in vivo were affected in opposite directions." (PMID 35163478, 2022). "Together, DLK2 may act as a potent therapeutic target for ccRCC control by modulating the oncogenic processes of tumor cell and the tumor microenvironment." (PMID 35456435, 2022). "Moreover, aerobic metabolism in the mitochondria and the transcription of oncogenic miRNAs targets (possible tumor suppressor genes) may be shut down by DLK2 signaling." (PMID 35456435, 2022). "Vaccines targeting both DLK1 and DLK2 show superior antitumor benefits by promoting CD8+ T cells infiltrations and tumor vascular normalization." (PMID 35456435, 2022). "Second, arm-level gain of DLK2 gene reduced CD8+ T cells (*** p < 0.001), CD4+ T cells (** p < 0.01), macrophage (** p < 0.01), neutrophil (*** p < 0.001), and dendritic cell infiltrations (** p < 0.01) in tumor tissue." (PMID 35456435, 2022). "DLK2 may participate in ECM remodeling, ribosome biogenesis, the activation of TGF-β/Notch oncogenic signaling, gene transcriptional regulation, M1 to M2 polarization of macrophage, and the increment of tumor suppressor miRNAs targets (possible oncogenes)." (PMID 35456435, 2022).
bone disorder (1 paper, 2023). "A deficient Dlk2 level in osteoclasts effectively increased bone mass in ovariectomized mice, providing new insight into the prevention of osteoclast-related bone disorders." (PMID 37669921, 2023). "Our results reveal the important roles of the Dlk2-Syap1 signaling pathway in osteoclast differentiation and osteoclast-related bone disorders." (PMID 37669921, 2023).
DLK2 also shares sentences with these, for which no sentence is quoted: Alzheimer disease (1 paper); breast tumors (1); Clear Cell Renal Cell Carcinoma (1); lung carcinoma (1); metastatic disease (1).